CCKBR (cholecystokinin B receptor)
Description:
Receptor for the peptide hormones gastrin and cholecystokinin (CCK). Expressed throughout the central nervous system, where it modulates processes such as anxiety, analgesia, arousal and neuroleptic activity. Couples to both GNAI1 and GNAQ signaling pathways, but not to GNAS. Upon gastrin activation, reduces glucose absorption in intestinal epithelial cells by downregulating SGLT1 and GLUT2 expression through suppression of the PI3K/Akt/eIF4B pathway (By similarity). In the kidney, decreases SGLT2 expression under high-glucose conditions via ERK/NF-kappa-B signaling (By similarity). Isoform 2 is constitutively activated and may regulate cancer cell proliferation via a gastrin-independent mechanism.
Synonyms: CCK-BR; CCK2R; GASR; CCK-2R; CCK-B
Tractability: Small molecule: an approved drug acts on it; a high-quality ligand is known; it belongs to a druggable protein family. Antibody: its Gene Ontology location is reachable by antibodies, with high confidence; UniProt places it where antibodies can reach, with medium confidence; UniProt predicts a signal peptide or a membrane-spanning region. PROTAC: a small molecule that binds it is known. Other modalities: a drug acting on it is in phase 2 or 3 trials.
Target class: Short peptide receptor (family A GPCR); Peptide receptor (family A GPCR); Cholecystokinin receptor; Family A G protein-coupled receptor; Membrane receptor
Chemical probes: GI-181771X, L-365260 (high quality)
Safety:
Unwanted effects reported when the protein is acted on. In parentheses: how it was acted on, where the effect was seen, and who reports it.
anxiety (activation; central nervous system; source: Brennan et al. (2024))
dyspepsia (inhibition; gastrointestinal; source: Brennan et al. (2024))
flatulence (inhibition; gastrointestinal; source: Brennan et al. (2024))
higher incidence of diarrhoea (inhibition; gastrointestinal; source: Brennan et al. (2024))
Hypergastrinaemia (inhibition; gastrointestinal; source: Brennan et al. (2024))
increased gastric pH due to suppression of gastric acid secretion (inhibition; gastrointestinal; source: Brennan et al. (2024))
nausea (inhibition; source: Brennan et al. (2024))
Gene: Protein-coding gene on chromosome 11 (6,259,806 to 6,272,127, forward strand). Ensembl gene ENSG00000110148.
Subcellular location: Cell membrane
Subcellular location (Human Protein Atlas): Vesicles; Plasma membrane
Pathways (Reactome):
Signal Transduction: G alpha (q) signalling events; Gastrin-CREB signalling pathway via PKC and MAPK; Peptide ligand-binding receptors
Gene Ontology:
Molecular function: cholecystokinin receptor activity; gastrin receptor activity; peptide hormone binding; protein binding; type B gastrin/cholecystokinin receptor binding; 1-phosphatidylinositol-3-kinase regulator activity; neuropeptide receptor activity; G protein-coupled receptor activity
Biological process: cholecystokinin signaling pathway; G protein-coupled receptor signaling pathway; phospholipase C-activating G protein-coupled receptor signaling pathway; positive regulation of cell population proliferation; positive regulation of cytosolic calcium ion concentration; cell surface receptor signaling pathway; neuropeptide signaling pathway
Cellular component: plasma membrane; membrane
Genetic constraint (gnomAD): Loss-of-function variants: 33 observed, 37.39 expected, observed/expected ratio (o/e) 0.88, 90% interval 0.67 to 1.18. The upper end of that interval is the gene's LOEUF score, 1.18, which puts it in group 5 of 6, group 1 being the genes least tolerant of losing a copy. Missense variants: 652 observed, 634.2 expected, observed/expected ratio (o/e) 1.03, 90% interval 0.96 to 1.1. Synonymous variants: 269 observed, 271.76 expected, observed/expected ratio (o/e) 0.99, 90% interval 0.89 to 1.1.
Homologues: Orthologues: macaque CCKBR (97% identical), rabbit CCKBR (94% identical), dog CCKBR (90% identical), rat Cckbr (90% identical), mouse Cckbr (89% identical), guinea pig CCKBR (87% identical), tropical clawed frog cckbr (52% identical), zebrafish cckbra (49% identical), zebrafish cckbrb (47% identical), Drosophila melanogaster CCKLR-17D3 (32% identical), Drosophila melanogaster CCKLR-17D1 (31% identical). Paralogues in human: CCKAR (46% identical), NPFFR1 (23% identical), HCRTR2 (22% identical), HCRTR1 (21% identical), OXTR (21% identical), AVPR1B (20% identical), NPFFR2 (20% identical), QRFPR (20% identical), GALR3 (20% identical), GALR1 (20% identical), AVPR2 (19% identical), AVPR1A (19% identical), and 4 more.
Diseases named in the same sentence as CCKBR in open-access papers:
CCKBR is named in the same sentence as 114 diseases in open-access papers, as found by Europe PMC text mining. Sharing a sentence is not in itself a finding about the gene and the disease. The quoted sentences say what the papers report.
Anxiety (33 papers, 2008 to 2025). Intense feelings of nervousness, tension, or panic often arise in response to interpersonal stresses. "Previous studies have indicated that the genetic inactivation of CCKBR causes deficits in the gastrointestinal system, control of food intake, memory and exploration, and anxiety-related behaviors." (PMID 37808112, 2023). "The findings may verify that social pressure causes anxiety by increasing the CCKBR hormone, which can induce crowing sounds in chickens." (PMID 40568511, 2025). "CCKBR has been demonstrated in the literature to play an essential role in anxiety and panic disorder." (PMID 38999998, 2024). "The effectiveness of the small non-opiate scFv antibody targeting the cholecystokinin B receptor (CCK-BR) alleviation of chronic orofacial hypersensitivity is sufficient to prevent development of anxiety and depression in the chronic model." (PMID 37446213, 2023). "Previous studies have also revealed that when mammals and chickens are subjected to intracerebroventricular administration of an agonist specific for CCKBR, stress-like anxiety behavior is observed immediately." (PMID 30850691, 2019). "Similarly, that CCK-like receptor knockdowns reduce fly anxiety supports the hypothesis that CCK receptors are involved in anxiety and fear, with a role proposed specifically for the mammalian cholecystokinin B receptor (CCKBR)." (PMID 27020741, 2016). "Cholecystokinin B receptor (CCKBR) and cholecystokinin (CCK) in sensory ganglia, spinal cord, and supraspinal neurons mediate nociception, morphine insensitivity, and anxiety in numerous rodent pain models." (PMID 38999998, 2024). "We reproduced and expanded our earlier findings in an animal model of GABBR1, CCKBR, and DYNLL2 as top genes involved in anxiety." (PMID 36878964, 2023). "CCKBR is a G protein-coupled receptor for gastrin and cholecystokinin (CCK), which primarily regulates anxiety, feeding, and locomotion in the brain." (PMID 29770110, 2018). "Furthermore, overexpression of CCKBR in the mouse brain increased aggressive behavior, while mice lacking CCKBR displayed increased exploratory behavior and reduced anxiety." (PMID 25566191, 2014).
gastric cancer (27 papers, 2010 to 2025). A primary or metastatic malignant neoplasm involving the stomach. "A close relationship between gastric NENs and adenocarcinomas of the stomach has been described, and the preservation of the CCKBR on gastric cancer cells may similarly to gastric NETs make them susceptible for treatment with a CCKBR antagonist (netazepide)." (PMID 28980157, 2018). "The gastrointestinal peptide gastrin has been shown to stimulate growth of gastric cancer in a paracrine and autocrine fashion through the cholecystokinin-B receptor (CCK-BR), a receptor that is expressed in at least 56.6% of human gastric cancers." (PMID 34926305, 2021). "We wished to explore this further by examining the expression of CCKBR in gastric cancer, including neuroendocrine neoplasms (NENs) and gastric carcinomas of the diffuse and intestinal types." (PMID 28980157, 2018). "miR-148b, which is frequently down-regulated in gastric cancer, can suppress gastric cancer cell growth by targeting the cholecystokinin-B receptor." (PMID 28159933, 2017). "In gastric cancer, miR-148b inhibited cell proliferation in vitro and in vivo by lowering the levels of cholecystokinin-B receptor (CCKBR), a protein that promotes tumorigenesis." (PMID 23325049, 2013). "Detection of intracellular signal substances will not necessarily prove that gastrin has a positive trophic effect on gastric cancer cells; thus, biological effects of gastrin are better demonstrated by confirming an inhibitory effect of a CCKBR antagonist on such tumors in vivo." (PMID 28980157, 2018). "In addition, the expression of CCKBR is regarded as a symbol that has a close relationship with gastric canceration." (PMID 30382864, 2018). "Therefore, the determination of CCKBR (gastrin receptor) in gastric carcinoma cells will help to select patients for treatment trials with netazepide and is also important for the understanding of gastric carcinogenesis." (PMID 28980157, 2018). "The aim of our study was to explore whether CCKBR is expressed in stomach cancers." (PMID 28980157, 2018). "Thus, targeting the CCKBR may be an option when treating carcinomas of the stomach, and perhaps this may improve the now dismal prognosis of this disease." (PMID 28980157, 2018). "Therefore, we propose that miR-148b may have an effect on proliferation in gastric cancer, depending on regulating the expression of CCKBR." (PMID 21205300, 2011). "We utilized two gastric cancer cell lines, MKN45 that expresses the CCKBR endogenously and the AGS-Gr that stably overexpresses the CCKBR." (PMID 28109268, 2017). "Therefore, we asked whether CCKBR has an effect on gastric cancer cell growth." (PMID 21205300, 2011). "In addition, we measured CCKBR protein levels in 49 pairs of the previously studied 106 gastric cancer tissues and their matched non-tumor adjacent tissues, which had already been verified as expressing miR-148b by qRT-PCR." (PMID 21205300, 2011).
pancreatic cancer (26 papers, 2006 to 2025). "We have been studying the role of a G-protein coupled receptor, the cholecystokinin-B receptor (CCK-BR), and its signaling pathways in pancreatic cancer." (PMID 34638432, 2021). "Our research team has identified the cholecystokinin-B receptor (or CCK-BR) as a novel target for treatment of pancreatic cancer." (PMID 34638432, 2021). "We discovered that a G-protein coupled receptor called the cholecystokinin-B receptor (CCK-BR) is rare in the normal mouse and the normal human pancreas, but this receptor becomes over-expressed in PanIN lesions and is markedly over-expressed in pancreatic cancer." (PMID 34944412, 2021). "Our research laboratory has found that the G-protein coupled rhodopsin receptor, the cholecystokinin-B receptor (CCK-BR), is upregulated in pancreatic cancer and plays an important role in cancer growth and fibrosis." (PMID 37345148, 2023). "The contributing genes to this pathway, e.g. CCKBR, CHRM5, EDNRA, LPAR1, SSTR2/3, and SCTR, have diverse functions in regulating the endocrine and exocrine functions of the pancreas, which are highly relevant to pancreatic cancer." (PMID 23056513, 2012). "We designed a biodegradable nanoparticle polyplex (NP) micelle that selectively targets the cholecystokinin-B receptor (CCK-BR), growth factor receptor that is markedly over-expressed in pancreatic cancer and not detected in the normal pancreas." (PMID 36614194, 2023). "The cholecystokinin-B receptor (CCK-BR) is absent in the normal pancreas but becomes expressed in high grade PanIN lesions and is over-expressed in pancreatic cancer making it a prime target for therapy." (PMID 36614194, 2023).
medullary thyroid carcinoma (25 papers, 2011 to 2026). "Importantly, high expression of CCKBR was previously validated in a variety of cancers including medullary thyroid cancer (MTC), small cell lung, colon and ovarian cancers as well as in gliomas 4-7." (PMID 33042258, 2020). "Gastrin acts as a potent cell-growth factor and has proliferative effects on various malignancies including gastric, colorectal, pancreatic, medullary thyroid cancers and small cell lung cancer, as well as tumors of the central and peripheral nervous systems through CCKBR." (PMID 21205300, 2011).
small cell lung carcinoma (23 papers, 2011 to 2026). Small cell lung cancer (SCLC) is a highly aggressive malignant neoplasm, accounting for 10-15% of lung cancer cases, characterized byrapid growth, and early metastasis. "We have recently developed the 225Ac-labeled minigastrin analog 225Ac-PP-F11N, which targets overexpressed cholecystokinin B receptor (CCKBR) in various human cancers including medullary thyroid, ovarian, and small-cell lung cancer, as well as gliomas." (PMID 36732057, 2023). "The overexpression of cholecystokinin B receptor (CCKBR) has been previously found in different types of tumors, including medullary thyroid carcinoma (MTC), stromal ovarian cancer, small-cell lung cancer, and astrocytoma." (PMID 33198403, 2020). "CCKBR, also called CCK2R, has proliferative effects on various cancer, such as gastric, colorectal, pancreatic and small cell lung cancer through gastrin." (PMID 23683438, 2013).
colorectal cancer (14 papers, 2002 to 2024). A primary or metastatic malignant neoplasm that affects the colon or rectum. "CCKBR belongs to the family of G-protein-coupled receptors (GPCRs) and its activation was further reported in pancreatic and colorectal cancer, in which CCKBR signaling played an important role in cancer cell proliferation." (PMID 34959437, 2021). "The expression of CCKBR, HOXC6, and POU4F1 were significantly higher in colorectal cancer cell lines compared to those in FHC cells." (PMID 36176299, 2022).
colon carcinoma (9 papers, 2016 to 2025). "Since activation of CCKBR has recently been shown to promote the stemness of colon cancer cells, it is possible that the induction of CCK expression by adipocytes may lead to the activation of an autocrine loop and as a result promote CSC self-renewal." (PMID 26700819, 2016). "In a cohort of patients with colon cancer, with and without T2D (Accession No: GSE115313), the diabetic intestine had decreased CCKBR mRNA." (PMID 39950948, 2025).
gastric adenocarcinoma (7 papers, 2005 to 2025). "A Danish study assessed CCKBR mRNA by real time PCR and receptor protein by western blotting in 20 gastric adenocarcinomas and found both in all tumors." (PMID 28980157, 2018). "Collectively, the data demonstrates that the gastric adenocarcinoma cell lines display an increased autophagy in response to gastrin in a CCKBR dependent manner." (PMID 28109268, 2017). "Although a substantial part of the gastric adenocarcinomas express gastrin and CCKBR, the role of gastrin in tumor development is not completely understood." (PMID 28109268, 2017).
pancreatic adenocarcinoma (7 papers, 2011 to 2025). "One study investigated a common cholecystokinin-B receptor (CCKBR) intronic variant in pancreatic adenocarcinoma within a Hungarian cohort." (PMID 40004893, 2025).
panic disorder (7 papers, 2012 to 2025). An anxiety disorder characterized by multiple unexpected panic attacks with persistent concern of recurring attacks. "MCS has prominent features of panic disorder, a disorder for which the cholecystokinin B receptor (CCK-B) has been implicated." (PMID 35053790, 2021). "Moreover, the CCKBR agonist CCK-tetrapeptide (CCK-4) induces acute panic attacks in healthy human subjects and patients with a panic disorder." (PMID 34779397, 2021).
diabetes (5 papers, 2013 to 2025). "What database, referenced in GeneCards, contains the CCKBR-diabetes association?" (PMID 23633938, 2013). "We also examined the small and large intestinal CCKBR expression in established experimental models of diabetes, e.g., T2D induced by high‐fat diet (HFD)." (PMID 39950948, 2025).
gastric NETs (5 papers, 2013 to 2024). "The CCKBR antagonist, netazepide, aids in preventing the formation of gastric NETs in mastomys." (PMID 28980157, 2018).
breast carcinoma (4 papers, 2018 to 2022). "It is highly reasonable to speculate CCKBR/ERK/P65 cascade may play a role in breast cancer development." (PMID 30115027, 2018).
melanoma (4 papers, 2021 to 2024). A malignant, usually aggressive tumor composed of atypical, neoplastic melanocytes. "In line with the protein data, elevated CCKBR gene expression was statistically linked to stage III–IV melanomas compared to early stage I–II melanomas when examining the CCKBR-expressing subset of the melanoma TCGA PanCancer dataset (PMID: 29625048)." (PMID 38069171, 2023). "Furthermore, among the 219 tumors in the Skin Cutaneous Melanoma TCGA Pan-Cancer dataset showing gastrin receptor (CCKBR) expression, significantly higher CCKBR mRNA levels were linked to stage III–IV than stage I–II melanomas." (PMID 38069171, 2023). "Flow cytometric analysis revealed that B16-F1 mouse melanoma and A375 human melanoma cells expressed CCKAR, whereas CCKBR was hardly detected in these cells." (PMID 36262666, 2022). "Flow cytometric analysis revealed that CCKAR but not CCKBR was present in the melanoma cell lines (B16-F1 and A375) and A431 SCC cells, whereas HSC-1 SCC cells expressed both CCKAR and CCKBR." (PMID 36262666, 2022).
atrophic gastritis (3 papers, 2013 to 2018). "The CCKBR antagonist netazepide also reduces the density of ECL cells in flat gastric mucosa in those patients with NETs due to atrophic gastritis." (PMID 28980157, 2018).
carcinoids (3 papers, 2013 to 2019). "The expression of cholecystokinin 2 receptor (CCK2R, CCKBR or gastrin receptor) has been reported on a diverse range of cancers such as colorectal, liver, lung, pancreatic, ovarian, stomach, thyroid and numerous neuroendocrine/carcinoid tumors." (PMID 26910279, 2016).
Hypertension (3 papers, 2016 to 2022). The presence of chronic increased pressure in the systemic arterial system. "Genome-wide association studies showed that the chromosomal loci of gastrin and CCKBR were linked to hypertension." (PMID 28420122, 2017). "Disruption of CCKBR in mice caused hypertension and decreased sodium excretion." (PMID 26751218, 2016). "Our results demonstrate that knockout of gastrin receptor (CCKBR) gene in mice results in high blood pressure that can be aggravated in response to an oral salt load, which is in accordance with an early study." (PMID 26751218, 2016). "Indeed, D1-like receptors, such as D1 dopamine receptor, and CCKBR synergistically increase sodium excretion in normotensive but not in spontaneously hypertensive rats, suggesting that the dysregulation of interaction between gastrin and CCKBR may be a mechanism in hypertension progress." (PMID 28420122, 2017).
lung carcinoma (3 papers, 2016 to 2017). "Gastrin exerts a growth promoting effect on several gastrointestinal cancer cells and a variety of neoplasms that express CCKBR, including neuroendocrine, pancreatic, medulla thyroid and lung cancer." (PMID 28109268, 2017). "In regards to lung cancer, CCKBR is expressed in both SCLC and NSCLC." (PMID 29262666, 2017). "However, CCKBR mRNA was detectable in lung cancer, including SCLC, adenocarcinoma and squamous cell carcinoma." (PMID 29262666, 2017).
Obesity (3 papers, 2024 to 2025). Accumulation of substantial excess body fat. "When CCKBR is knocked out systemically in mice, it leads to obesity characterized by increased food intake and fat accumulation due to adipocyte hypertrophy." (PMID 39529694, 2024).
pancreatic ductal adenocarcinoma (3 papers, 2013 to 2023). An infiltrating adenocarcinoma that arises from the epithelial cells of the pancreas. "Pancreatic ductal adenocarcinomas (PDACs) constitutively express the G-protein-coupled cholecystokinin B receptor (CCKBR)." (PMID 27754762, 2017). "The peptide growth factor gastrin and its receptor, the G-protein coupled cholecystokinin receptor type B (CCKBR), play an integral role in the growth and progression of pancreatic ductal adenocarcinoma (PDAC)." (PMID 25346875, 2013).